USP9X (ubiquitin specific peptidase 9 X-linked)
Diseases named in the same sentence as USP9X in open-access papers (continued):
Sharing a sentence is not in itself a finding about the gene and the disease.
tumor (100 papers, 2010 to 2026). "On the contrary, re-expressed HIF-2α efficiently recovered the tumor cell migration, spheroid formation efficiency and CSCs proportion defects caused by USP9X knockdown, respectively." (PMID 40246814, 2025). "Clinical data analysis showed that abnormally high expression of USP9X was closely associated with high tumor grade and poor survival rate, and USP9X was positively correlated with RHOA protein expression levels." (PMID 41291745, 2025). "USP9X deficiency: Located on Xp11.4, USP9X is a tumor suppressor and oncogene that regulates the ubiquitylation of various cellular substrates." (PMID 40722698, 2025). "Preclinical studies have observed reductions in Notch signaling after treatment with G9, a small-molecule USP9x inhibitor, together with remodeling of the tumor-associated immune environment and decreased tumor growth, with minimal toxicity." (PMID 38811720, 2024). "Of interest, inhibition of USP9X activity by the small-molecule inhibitor DUB G9 also appears to have susceptibility to tumor growth in NRAS mutant lines compared to BRAF lines in vivo and in vitro." (PMID 35884430, 2022). "Although depletion of USP9X reduces tumor growth in melanoma cells carrying BRAF or NRAS mutations, its combination with MAPK pathway inhibitors (vemurafenib or MEKi) has been shown to enhance the therapeutic response." (PMID 35884430, 2022). "In OSCC, USP9X can bind to PD-L1 to induce its deubiquitination, ultimately causing tumor cells to escape T cell attack." (PMID 35836933, 2022). "The genome profiling of 60 gingival SCCs revealed that approximately 20% of oral SCC tissues harbors copy number loss and truncating mutations in USP9x locus consistent with a potential role as a tumor suppressor." (PMID 32560247, 2020). "c-Myc heterozygosity abrogated increased progenitor proliferation and tumor burden in Usp9x-deficient mice, suggesting that Usp9x suppresses tumor formation by regulating Fbw7 protein stability and thereby reducing c-Myc." (PMID 29346117, 2018). "Usp9x depletion blocked expansive tumour growth in matrigel, particularly in tumours with NRAS mutations." (PMID 28198367, 2017). "Contrasting these results, it was shown that in conditional knock-out mice the loss of Usp9X paradoxically entertained tumor growth in the presence of mutated Kras (G12D)." (PMID 26872380, 2016). "They found USP9X knockdown alone caused a modest decrease in tumour growth but specifically stabilized MCL1 by removing its degradative Lys 48-linked polyubiquitin chains to promoting cell survival." (PMID 24152793, 2013). "Interestingly, several studies have reported that USP9X mainly controls cell adhesion and polarity, which has been implicated in neurodegenerative disease and tumor 51,52." (PMID 40963913, 2025). "A recent study showed that mutations in USP9X increase sensitivity to mTOR inhibition, suggesting that mTOR inhibitors may represent a therapeutic approach for tumours harbouring USP9X mutations." (PMID 38785992, 2024). "Sox2 associated with USP9X regulates the growth of tumor cells in the brain." (PMID 33158118, 2020). "The same approach was used by other investigators reporting the identification of the X-linked deubiquitinase USP9X as the gene most frequently mutated in KRAS mice submitted to insertional mutagenesis: loss of USP9X gene enhances transformation and promotes tumor progression." (PMID 29156578, 2017). "In conclusion, our study provides the first evidence for negative regulation of the pVHL-HIF pathway by USP9X through the novel pVHL E3 ligase Smurf1, which induces degradation of pVHL and its unstable mutants to promote progression of pVHL associated neoplasms." (PMID 27517496, 2016). "However, the loss of USP9X may be harmful to the growth of tumor cells, but its loss in primary tumor cells may accelerate the development of secondary tumors." (PMID 36613989, 2022).
tumor (continued). "USP9X expression was a significantly independent prognostic factor (P = 0.002) with a relative risk of 0.365 (95% confidence interval, 0.193 – 0.688) in a Cox multivariate analysis, which was performed with the following variables for each case: USP9X expression, radiotherapy and tumor size." (PMID 27783990, 2016). "We also evaluated the function of USP9X in tumor cells and found that knockdown of USP9X expression significantly inhibited the migration and invasion of MDA-MB231 and SUM159 cells in vitro." (PMID 41291745, 2025). "For instance, in lung cancer, USP9X drives tumor progression by stabilizing the oncoprotein lysine-specific demethylase 4C (KDM4C)." (PMID 41301681, 2025). "Consistent with the functions in vitro and in bulk cell population, within both in vivo imaging and anatomical assays, USP9X deprivation suppressed the tumor regeneration and intraperitoneal metastasis capability of CSCs." (PMID 40246814, 2025). "More importantly, we found that the hypoxia tumor microenvironment activates the TGF-β-USP9X-HIF-2α CSCs regulatory axis." (PMID 40246814, 2025). "Antagonizing USP9X efficiently represses tumor formation, metastasis, while increases chemo-sensitivity through patient derived xenograft (PDX), organoid models and chemoresistant cell models." (PMID 40246814, 2025). "Consistent with the subcutaneous model, knockdown of HDAC6 and USP9X notably suppressed GBM tumor growth and reduced Ki‐67 and GS expression in the intracranial model." (PMID 40162736, 2025). "The study revealed that USP9X, a deubiquitinase, forms a multiprotein complex with tribbles homolog 3, a pseudokinase, under cellular stress conditions commonly found in the tumor microenvironment and jointly activates the Notch pathway." (PMID 40034124, 2025). "This study further demonstrates USP9X’s tumor-suppressive function in CCA, mediated through EGLN3 stabilization." (PMID 41301681, 2025). "Whereas, epithelial marker, E-cadherin, declined with tumor grading, sharply contrasting those of p-Smad3 and USP9X." (PMID 40246814, 2025). "In the current study, antagonizing USP9X by inhibitor WP1130 efficiently represses tumor formation, CSCs content, TGF-β signaling thus increases chemosensitivity through organoids, PDX, and chemoresistant cell models." (PMID 40246814, 2025). "Through our stained and blotted OC cohorts, USP9X was parallelly expressed with p-Smad3 and positively correlated with tumor grading." (PMID 40246814, 2025). "We found that genetic silencing of USP9x resulted in a drastic reduction of tumor growth and tumor weight in vivo." (PMID 39075050, 2024). "While the normal lung tissues displayed 64% of high expression of USP9x, the expression was elevated to 87% in the tumor samples." (PMID 39075050, 2024). "USP9X has been shown to regulate EGFR endocytosis in tumor cell lines by deubiquitinating its endocytic adaptor Eps15 and ubiquitin ligase Itch." (PMID 36653359, 2023). "The high expression of USP9X in OSCC cells increases the stability of PD-L1 in OSCC cells by deubiquitinating the tumor and promoting immune escape." (PMID 37554324, 2023). "As a member of DUBs, ubiquitin-specific peptidase 9, Xlinked (USP9X) has a role in the control of tumor cell proliferation, adhesion, and apoptosis, among other things." (PMID 37554324, 2023). "To date, USP9X has been found to be present at abnormal levels in many different tumor types including digestive tract tumors, respiratory tract tumors, hematological tumors, and genitourinary tumors." (PMID 37057289, 2023). "USP9X activity and expression were found to be elevated in metastases compared to those in the primary tumor." (PMID 35884430, 2022). "Using paired normal and tumor DNA from the same patients, we identified and validated a few novel recurrent somatic mutations in LGSOC, in addition to KRAS, BRAF, USP9X, and EIF1AX mutations that have been identified in previous studies." (PMID 36528667, 2022).
tumor (continued). "USP9X has been shown to promote Mcl-1 stabilization and to increase tumor cell survival in response to radiation and chemotherapy in several tumor types." (PMID 34277417, 2021). "Depletion or inhibition of USP9X led to reduced ERG expression that was linked to impaired PCa signature gene expression and the inhibition of ERG-positive tumour growth in mouse xenograft models." (PMID 34066106, 2021). "Suggested that Usp9x activity and expression were elevated in metastatic as compared to primary tumor and correlated with elevated SOX2 levels." (PMID 33613844, 2021). "The tumor weight was significantly increased in the USP9X-silenced groups than in the control groups." (PMID 34112167, 2021). "Intriguingly, USP9X suppresses tumor growth by deubiquitinating and potentiating LATS kinase, a component in the Hippo pathway." (PMID 34575114, 2021). "WP1130 induces tumor cell apoptosis through inhibiting USP9X, therefore decreasing the protein level of one other substrate of USP9X, antiapoptotic protein MCL-1." (PMID 33466790, 2021). "This resistance behavior can be reversed by USP9X knockdown, which signals rapid degradation of Mcl−1 and induces apoptosis in radioresistant tumor cells." (PMID 33158118, 2020). "Our past work has shown that CP-dn-ATF5 dramatically reduces USP9X levels in multiple tumor cell lines including T98G cells." (PMID 31551409, 2019). "Considering the possible tumor suppressor role of USP9X and oncogene role of USP24 in T-ALL and the feedback regulation between USP9X and USP24, developing a USP24 specific inhibitor is needed." (PMID 30911287, 2019). "Genetic and/or pharmacological inhibition of Usp9X activity has been shown to induce tumor cell death in both in vitro and in vivo models of GBM6–8." (PMID 30478285, 2018). "In the same study, it was observed that MCL-1 levels were increased in malignant tissues from melanoma patients while Beclin1 was destabilized, suggesting that USP9X promotes tumor progression." (PMID 30126257, 2018). "Based on its tissue-specific roles in both tumor promotion and suppression, we focused on USP9X for further validation and biochemical evaluation." (PMID 29346117, 2018). "Our data demonstrate that in addition to the pancreas, USP9X is also a tumor suppressor in the intestine." (PMID 29346117, 2018). "Taken together, these data support the notion that USP9X acts as a tumor suppressor in the intestine via positive regulation of FBW7." (PMID 29346117, 2018). "The results suggest that USP9X not only can increase the level of PD‐L1 but also plays an important role in tumor growth." (PMID 29992764, 2018). "In CRC tumor tissue, USP9X and FBW7 showed a strong correlation in staining intensity, with 72% showing concomitant downregulation (case 1)." (PMID 29346117, 2018). "Only one animal (of 3) had detectable tumour (shown) in mice injected with Usp9x KD cells, while control tumours grew to maximal burden in all 3 animals." (PMID 28198367, 2017). "As expected, either Ets-1 or Usp9x overexpression in SK-Mel29 cells increased 3D tumour growth, while Ets-1 KD blocked both control and Usp9x-enhanced 3D growth and colony formation." (PMID 28198367, 2017). "Collectively, these observations suggest a potential role for USP9X-promoted CEP131 stabilization in breast carcinogenesis." (PMID 28361952, 2017). "Conversely, tumor suppressive function of USP9X has been demonstrated in pancreatic ductal adenocarcinomas that contain KRAS mutations." (PMID 28101374, 2017). "Usp9x inhibition is expected to add to the treatment options for patients with Ets-1-overexpressing tumours, particularly when used in rational, biologically based combinations." (PMID 28198367, 2017). "Intriguingly, both oncogenic and tumor suppressive functions of USP9X have been reported, likely due to genetic background differences across multiple tumor types and stages." (PMID 28101374, 2017).
tumor (continued). "We demonstrate that dysregulation of USP9X contributes to centrosome amplification, chromosome instability and breast carcinogenesis." (PMID 28361952, 2017). "Inhibiting USP9X using the small molecule WP1130 triggers tumor cell apoptosis, potentially by decreasing the MCL-1 protein level." (PMID 28101374, 2017). "Within this cohort USP9X expression was higher in tumor tissues compared with normal tissues (lung, p < 0.0001; breast, p < 0.0001; urinary bladder, p = 0.0025)." (PMID 27517496, 2016). "al. noted that miR-26b inhibited EMT and acts as tumor suppressor by negatively regulating USP9X in HCC." (PMID 27027434, 2016). "Based on these results, we propose USP9X suppresses tumor progression through negative regulation of pVHL." (PMID 27517496, 2016). "Suppression of glycolysis by USP9X knockdown supports our supposition that USP9X plays a role in induction of anaerobic metabolism in tumor cells." (PMID 27517496, 2016). "This study shows that inhibition of USP9X function by either shRNA or a chemical inhibitor significantly enhances pVHL levels and suppresses tumor cell proliferation." (PMID 27517496, 2016). "Another recent report links Usp9X to Beclin-1, a gene that is known as a tumor suppressor and a modulator of autophagy." (PMID 26008975, 2015). "This fact is highlighted by the apparent contradiction is some reported USP9X roles, for example, both promoting and inhibiting TGFβ signalling, acting in both pro- and anti-apoptotic pathways and displaying both oncogenic and tumour suppressor functions." (PMID 25672900, 2015). "In contrast, deubiquitinase USP9X, which is overexpressed in some malignancies, stabilizes Mcl-1 and promotes tumor cell survival." (PMID 24529193, 2014). "The aim was to detect the expression of USP9X in the progression from normal epithelium to invasive esophageal squamous cell cancer (ESCC) and evaluate the relevance of USP9X expression to the tumor progression and prognosis." (PMID 24152793, 2013). "In conclusion, we have identified >280 proteins that associate with SOX2 in DAOY MB tumor cells and demonstrate that two of the SOX2-associated proteins, MSI2 and USP9X, play key roles in the growth of MB and GB cells." (PMID 23667531, 2013). "Mcl-1, Bcl-xL and USP9X overexpression are tumor survival mechanisms protective against chemotherapy." (PMID 23171055, 2012). "Promoting Mcl-1 ubiquitination and degradation using USP9X inhibitor sensitizes tumor cells to various chemotherapies including Bcl-2/Bcl-xL inhibitors." (PMID 23171055, 2012). "USP9X inhibition increases tumor cell sensitivity to various chemotherapeutic agents including Bcl-2/Bcl-xL inhibitors." (PMID 23171055, 2012). "We observed that UCHL1 expression directly correlated (P<0.001) with tumor grade, gender and Ki67 expression, while USP9X expression directly correlated with Ki67 expression (P<0.001)." (PMID 21283576, 2011). "Therefore, USP9X is required for tumor development and metastasis in vivo, possibly due to its critical role downstream of TGF-β." (PMID 40246814, 2025). "However, USP9X also exhibits significant tumor-suppressive effects in certain digestive system cancers." (PMID 41301681, 2025). "Besides the previously identified DUB substrates such as CEP131, we found HIF-2α, the critical hypoxia mediator and tumor driver, was among the binding list of USP9X." (PMID 40246814, 2025). "Notably, the expression of USP9X was further increased in chemo-resistant cells upon CDDP or PTX re-treatment, which supports the significance of USP9X in tumor cells against chemotherapy." (PMID 40246814, 2025). "However, re-introduction of HIF-2α significantly restored the tumor initiation and metastasis of USP9X-null CSCs, accompanied with elevated markers." (PMID 40246814, 2025). "However, USP9X is a tumor suppressor in both the colon and pancreas, making USP9X inhibition unsuitable." (PMID 39851497, 2025).
tumor (continued). "Furthermore, by using multiple clinical models, especially therapies on patients-derived organoids or xenografts, we certify that antagonizing USP9X efficiently represses tumor formation, metastasis, CSCs occurrence, while increases chemosensitivity." (PMID 40246814, 2025). "Antagonizing USP9X efficiently represses tumor formation, metastasis, CSCs occurrence, while increasing chemosensitivity in orthotopic tumors, patient-derived xenograft (PDX), organoid, and chemoresistant cell models, in part via restricting TGF-β and hypoxia activities." (PMID 40246814, 2025). "On the other hand, certain DUBs such as A20 and USP9X function as tumor suppressors in CRC." (PMID 39678489, 2024). "USP9x-mediated stabilization of Mcl-1 protein levels by preventing its degradation was described before as a mechanism that increased apoptosis threshold in other tumor entities." (PMID 37173959, 2023). "The complement factor H-related (CFHR) protein family induces the ubiquitination of polo-like kinase 1 (PLK1) at lysine 209, BRCA1-associated protein 1 (BAP1) enhances genomic stability, and USP9X is found to restrain tumor growth in the patient-derived tumor xenograft (PDX) model." (PMID 38174069, 2023). "Future tumor therapy may involve the suppression of overexpressed USP9X and its related family of genes." (PMID 37057289, 2023). "USP9X elicited tumor suppressor role by preventing degradation of EGLN3." (PMID 34112167, 2021). "G9 inhibits Usp9x activity in vitro and in vivo, and leads to tumor inhibition and regression." (PMID 33613844, 2021). "USP9X expression was found to be correlated with tumor size." (PMID 34112167, 2021). "In addition, frequent USP9X mutations were observed in LGSOC, and further investigations indicated USP9X to be a tumor suppressor gene and a potential therapeutic target for LGSOC." (PMID 34680597, 2021). "USP9X has tumor suppressor functions via its genetic interaction with Kras." (PMID 34112167, 2021). "The suppressive regulation of USP9X in tumor is potentially important." (PMID 34112167, 2021). "However, a tumor suppressor role of USP9X has been documented in pancreatic, colorectal, and renal cancer." (PMID 34112167, 2021). "Thus, TRB3 acts as a sensor during tumor environmental stress and functions with USP9X to induce cell survival and tumor-promoting activities of Notch." (PMID 33158118, 2020). "Thus, USP9X functions indirectly as a tumor suppressor, by controlling the protein stability of FBW7." (PMID 29346117, 2018). "However, USP9X function in tumorigenesis appears to be more complex and context-dependent as independent studies have shown that USP9X can be either a tumor promoter or suppressor depending on the origin of the cells." (PMID 30126257, 2018). "USP9X can have both pro- and antitumorigenic functions depending on tumor type." (PMID 29346117, 2018). "Silencing USP9X in tumor cells further validated the correlation between PD‐L1 and USP9X." (PMID 29992764, 2018). "Suppressing the expression of USP9X blocks tumor cell growth." (PMID 29992764, 2018). "Notably, tumour growth in athymic mice receiving tumour transplants with depletion of either USP9X or CEP131 was greatly suppressed." (PMID 28361952, 2017). "Analysis of fresh tumour tissue from primary or metastatic sites by immunoblotting suggested that Usp9x positivity was more common in metastatic (8/9) than primary tumour (3/9) and correlated with higher Ets-1 (or its isoform) levels in most Usp9x-expressing tumours." (PMID 28198367, 2017). "Usp9x enforced expression increased tumour expansion by >2-fold over controls (red versus blue lines) and growth of Usp9x-overexpressing tumours could be blocked by in vivo G9 treatment (red versus green line)." (PMID 28198367, 2017). "A second report identified USP9x as a tumor suppressor in a K-RAS mouse model of PDA." (PMID 27462448, 2016).